STAT3 (signal transducer and activator of transcription 3)
Diseases named in the same sentence as STAT3 in open-access papers (continued):
Sharing a sentence is not in itself a finding about the gene and the disease.
tumor (continued). "The administration (intraperitoneal) of pectolinarigenin blocked STAT3 activation and impaired tumor growth and metastasis with superior pharmacodynamic properties." (PMID 35327559, 2022). "Activator protein 1 (AP-1), nuclear factor kappa B (NF-κB), and STAT3 are signaling pathways responsible for tumor growth." (PMID 36428575, 2022). "Next, mass flow cytometry (CyTOF) was used to confirm the protein level of Pdia4, Vegfa, Vegfb, Vegfc and phospho‐Stat3 in stromal subsets of GK1 tumour‐bearing WT and Pdia4–/– mice." (PMID 35170261, 2022). "Studies on the relationship between B lymphocytes and tumours, especially PC, have majorly focused on direct or indirect molecular targets, such as activation of STAT3 to promote tumour angiogenesis." (PMID 36578477, 2022). "The proinflammatory cytokines interleukin-6, expressed by tumour-associated macrophages, have been reported to be important to the development and progression of HCC by activating the transcription factor STAT3 and NF-κB pathways." (PMID 35255845, 2022). "Overall, rescue experiments confirm that the STAT3 signaling pathway is responsible for the tumor-suppressing effects of lncRNA HAR1A in NSCLC." (PMID 35740511, 2022). "In this paper, we illustrate findings on STAT3 proliferation, migration, anoikis resistance, radiation sensitivity, drug resistance, and the tumor microenvironment in NPC cells." (PMID 36313702, 2022). "The inhibition of constitutively active STAT3 suppressed tumor cell growth in vitro and tumor growth in vivo." (PMID 36473850, 2022). "It was suggested that IGFBP2 contributes to immune events in PDAC because it induces tumor progression via the enhancement of alternative macrophage polarization by regulating STAT3 signaling." (PMID 36556226, 2022). "We injected B16 tumor–bearing mice with control, Stattic-treated (STAT3 inhibitor), etomoxir-treated (CPT1A inhibitor), or Fer-1–treated (ferroptosis inhibitor) Tc9 cells." (PMID 35192544, 2022). "The signaling pathway of JAK/STAT3 and NF-κB have been universally recognized as the bridge linking tumor and inflammation." (PMID 36685973, 2022). "Studies have shown that STAT3 is a key transcription factor that supports macrophage differentiating into type 2 macrophage and greatly contributes to tumor progression." (PMID 36311792, 2022). "IL-6 overexpression is manifested by aberrant activation of STAT3 in tumor tissue, leading to decreased E-cadherin and increased vimentin protein expression." (PMID 36291659, 2022). "Given the fact that Stat3 is known to be hyperactive in a number of tumors, in tumor-derived cell lines as well as in cell lines transformed by a variety of oncogenes, it was expected that confluence-induced growth arrest would suppress Stat3 activity." (PMID 36010614, 2022). "Curcumin has been considered to suppress gastric carcinoma proliferation by inducing apoptosis in tumor cells and by inhibiting the STAT3, VEGF, and HIF1α signaling transduction pathways." (PMID 35211240, 2022). "On the one hand, activated STAT3 enhanced tumor cell proliferation by accelerating entry into S-phase." (PMID 35860554, 2022). "In particular, among STAT family members, STAT-3 seems to play a key role in tumor transformation and malignancy." (PMID 35203723, 2022). "Deletion of STAT3 in the NK compartment drastically improved tumor rejection, immune surveillance, and IFN-γ secretion abilities, and targeting STAT3 with microRNA-130a augmented NK cytotoxicity against NSCLC cells." (PMID 35406557, 2022). "In contrast, Sant‐1‐treated cells with constitutively activated STAT3 had up to 4 tumor colonies per culture dish, with an average number of 3.3 colonies (11‐fold higher than control, P < 0.05)." (PMID 34482626, 2022).
tumor (continued). "Intratumoral injection of STAT3 minicircles inhibited tumor growth and metastasis in a murine model of TNBC." (PMID 35847174, 2022). "GSCs mediate the adaptive immune system T-cell responses via the STAT3 pathway, which, as previously discussed, is a key regulator of tumor-mediated immune suppression." (PMID 35203636, 2022). "On the other hand, we describe the multiple functions of STAT3 in regulating NK-cell cytotoxicity, cytokine production and their anti-tumor responses in vivo." (PMID 35865518, 2022). "Since Pdia4 and Stat3 were present in stromal cells and tumour cells, CyTOF data showed that WT stroma had a higher level of phospho‐Stat3, Vegfa, Vegfb and Vegfc than Pdia4–/– stroma." (PMID 35170261, 2022). "MiR-206 prevents the suppression of tumor angiogenesis, both in vivo and in vitro, by inhibiting the 14-3-3z/STAT3/HIF-1α/VEGF signaling pathway and preventing normal fibroblast to cancer-associated fibroblast conversion by downregulating VEGFA expression." (PMID 35885514, 2022). "PROTAC 74 potently degraded STAT3 xenograft tumours and achieved complete and durable tumour regression in mice." (PMID 35702041, 2022). "In this review, we provide an overview of the recent findings regarding the intrinsic and extrinsic roles of STAT3 during tumor progression." (PMID 36010693, 2022). "IL-6/JAK/STAT3 signaling is able to drive the proliferation, survival, invasiveness, and metastasis of tumor cells, leading to a poor clinical prognosis in many types of cancers." (PMID 35734424, 2022). "STAT3 has emerged as important target as it promotes tumor cell stemness, malignant transformation, uncontrolled proliferation, evasion of apoptosis, metastasis and most importantly for this scope of this review, immune evasion." (PMID 36700235, 2022). "Further, there appear to be differences in the mechanisms regulating MDSC function in tumors and peripheral lymphoid organs, such that inhibition of STAT3 in tumor-bearing mice resulted in depletion of MDSCs in spleens but not in tumors." (PMID 35476843, 2022). "Treatment with heteronemin or its combination with tetrac, has been shown to down-regulate the gene expression level of EGFR, STAT3, and genes involved in tumor cell movement." (PMID 35705962, 2022). "TAMs secret IL-6, and IL-6/signal transducer and activator of transcription 3 (STAT3) signaling pathway mediates the resistance in tumor to chemotherapy drugs." (PMID 35193986, 2022). "The significant increase in overall survival in the STAT3cKO model demonstrates the profound influence STAT3+ stromal fibroblasts have on mediating tumor progression and the immune microenvironment." (PMID 35803738, 2022). "It inhibits mRNA translation and has shown efficacy in pre-clinical models, where it inhibited tumor growth and expression of STAT3 downstream target genes." (PMID 35844493, 2022). "IL-6 deregulation in tumor cells reprograms the STAT3 pathway in metastatic cells and promotes the recruitment of myeloid suppressor cells and macrophage polarization toward a phenotype that allows tumor cells to escape immune system surveillance." (PMID 36497411, 2022). "STAT1 and STAT3 protein expression were strongly and positively correlated in the tumor cells and infiltrating immune cells." (PMID 35267462, 2022). "For instance, in glial cells, STAT3 exerts a tumor-suppressive effect with complete PTEN function, whereas in epidermal growth factor receptor (EGFR)vIII-positive tumors, it plays an oncogenic role, both of which are mediated by different signaling pathways." (PMID 36557902, 2022). "The tumor-bearing animals treated with resveratrol showed increased apoptosis via STAT3 signaling and nuclear factor-like 2 (Nrf2)/heme oxygenase-1 (HO-1) pathway reduction." (PMID 35805049, 2022).
tumor (continued). "In a variety of cancers, IL-6/JAK/STAT3 is overactivated, which promotes tumor cell proliferation, survival, invasiveness and metastasis and inhibits the antitumor immune response, which is related to the poor prognosis of tumors." (PMID 35359408, 2022). "STAT3, in turn, reportedly enhances cellular proliferation by modulating the expression of various genes necessary for tumor cells to survive, grow, and undergo metastasis/angiogenesis." (PMID 36080130, 2022). "Activated STAT3 plays an important role in tumor growth and survival, and in the suppression of antitumor immunity by enhancing the activity of Tregs and M2Ms." (PMID 34398301, 2022). "Stat3 signaling is thought to play a critical role in promoting tumor survival and progression, including metastasis." (PMID 35494068, 2022). "Phosphorylation of STAT3 at Tyr705 is critical for its homodimerization, nuclear localization, and transactivation, which can promote tumor cell proliferation via enhancing cell cycle-related protein expression." (PMID 36443287, 2022). "Recent studies have highlighted that STAT3 functions as a transcription factor to activate target gene transcription and thus promotes tumor cell proliferation, survival, invasion, angiogenesis and immunosuppression." (PMID 36151091, 2022). "By contrast, RT prevented tumor-induced elevation on IL-6 plasma concentration and oxidative damage markers on skeletal muscle, which attenuated STAT3 phosphorylation, all events that play a key role in skeletal muscle protein degradation." (PMID 35847939, 2022). "The induction of miR-21 by the IL-6/STAT3 pathway is essential for transforming non-tumor hepatocytes, implying a critical role in early HCC development during chronic HBV infection." (PMID 36142450, 2022). "For example, bone marrow fat cells secrete significant and regulated levels of IL-6, which promotes metastasis of tumor cells through the JAK2/STAT3 signaling pathway." (PMID 35498437, 2022). "Remarkably, the phosphorylation of STAT3 was reduced in tumour cells from napabucasin‐treated mice compared to that in vehicle‐treated mice." (PMID 35665592, 2022). "STAT proteins transduce signals to the nucleus where they function as transcription factors, with certain STAT proteins (STAT1) acting to increase anti-tumor immunity and others (namely STAT3) facilitating cancer-promoting inflammation." (PMID 35663547, 2022). "For instance, the application of IL-6 antibody reduced the tumor size stimulated by 17β-estradiol and decreased the expression of phosphorylated (p)- Stat3 in nucleus of EC cells." (PMID 36531027, 2022). "Mechanistically, tumor cells induced osteoclasts to secrete the IL-20RB ligand IL-19, and IL-19 stimulated IL-20RB–expressing tumor cells to activate downstream JAK1/STAT3 signaling, leading to enhanced proliferation of tumor cells in bone." (PMID 36006737, 2022). "MAL mediates the mesenchymal transition of GC cells by inhibiting the STAT3 pathway, thereby regulating the proliferation, metastasis and invasion of tumor cells." (PMID 35093120, 2022). "The STAT3 signaling pathway drives malignant transformation of cells and STAT3 activation has been observed in a variety of tumor cells." (PMID 40396025, 2022). "Although STAT3 plays a crucial role in normal cells, constitutive activation of STAT3 in most human malignancies drives transcription of unscheduled genes and the transcription products subsequently promote tumor progression." (PMID 36231093, 2022). "Aberrantly, phosphorylated STAT3 is also involved in tumor formation, development, and metastasis, which would influence the clinical outcome of patients." (PMID 35356799, 2022). "Tumor growth, as well as tumor‐associated macrophage polarization, depends on the status of the STAT1:STAT3 ratio." (PMID 34689394, 2022).
tumor (continued). "Curcumin (CUR) and its derivatives, one of the most commonly used natural compounds for cancer therapy, have been reported to inhibit the phosphorylation of STAT3 and its downstream genes, thereby inhibiting angiogenesis and tumor growth." (PMID 36559280, 2022). "Factors released from tumor cells feed forward to increase activation of NF-κB (NF-κB1), STAT3, and AP1 (JUN, JUNB, and FOS) in surrounding cells." (PMID 36134665, 2022). "IL-1 and IL-6 can regulate the carcinogenic transcription factors NF-κB and STAT3, which play important biological functions and can accelerate tumor growth and progression." (PMID 35634419, 2022). "To explore the mechanism by which APS promote the differentiation and immunosuppressive function of MDSC, we observed the effect of APS in the levels of p-STAT1 and p-STAT3 in MDSC which were sorted from tumor-bearing mice by flowcytometer." (PMID 36159871, 2022). "One of the key signaling pathways controlling this phenomenon is the IL-6/JAK/STAT3 axis, which enhances tumor proliferation and cell metabolism by upregulating this signaling pathway." (PMID 36091125, 2022). "Most studies indicate that STAT3 is an oncogene and that inhibiting STAT3 prevents tumor progression, but activation of STAT3 is essential for protecting the cardiac tissue, such as by promoting angiogenesis or reducing apoptosis." (PMID 35273164, 2022). "The compounds further inhibited Stat3 nuclear accumulation and promoted Stat3 perinuclear aggregation in the tumor cells." (PMID 35276290, 2022). "Blood LPS levels and downstream signaling molecule TLR4, COX-2, and p-STAT3 protein expression levels were reduced, which correlated with tumor drug resistance and invasion capabilities." (PMID 36267958, 2022). "Aberrant STAT3 activation in tumors contributes to tumor cell proliferation/survival, metastasis, and therapy resistance." (PMID 36324587, 2022). "According to the study by Ott and collages, STAT3-blockers were able to stop the progression of the tumor in a GBM animal model." (PMID 35954362, 2022). "Dual inhibition of MEK and STAT3 signaling results in the disruption of potential crosstalk disruption, which can effectively inhibit tumor growth in vitro and in vivo." (PMID 35614034, 2022). "Repression of PDLIM2 has been shown to continuously activate nuclear factor-κB and STAT3, eventually leading to tumorigenesis and tumor maintenance." (PMID 35121770, 2022). "The influence of IL-32 in tumor growth through the inactivation of NF-κB and signal transducer and activator of transcription 3 (STAT3) pathways have been mentioned earlier." (PMID 35281008, 2022). "The inhibition of STAT3 activation in tumor upregulated the expression of several pro-inflammation chemokines and cytokines, which resulted in the infiltration of leukocyte into the tumor." (PMID 35936759, 2022). "IL-6/JAK2/STAT3 pathway is more active in CD44+CD24- BC cells than in other tumor types, and inhibition of JAK2 reduces their numbers and prevents xenograft growth." (PMID 36591515, 2022). "Among them, we paid special attention to multiple immune pathways, including the inflammatory response, interferon gamma response, TNF-a signaling pathway and IL-6/JAK/STAT3 signaling, all of which had been shown to be closely related to tumor development." (PMID 35991547, 2022). "STAT3 is currently considered one of the most promising targets to combat CRC as its over-activation is found not only in the cancer cells but also in the tumor microenvironment." (PMID 36139106, 2022). "More recently, cell-permeable, STAT3 SH2 domain mimetics with promising anti-tumor effects have been designed." (PMID 35401182, 2022). "Activated STAT3 protein acted as a transcription factor to regulate cell proliferation, apoptosis, angiogenesis, tumor invasion and metastasis." (PMID 34582743, 2022). "STAT3 is an oncogenic transcription factor that plays an important role in the proliferation of tumor cells." (PMID 36000726, 2022).
tumor (continued). "To date, the tumor-promoting functions mediated by STAT3 signaling in NSCLC have been well-documented to promote cell survival, angiogenesis, drug resistance, cancer cell stemness, and cancer immune evasion." (PMID 36010693, 2022). "Certain platinum complexes have shown remarkable antitumor activity by their ability to inhibit STAT3 in a variety of tumor models (Lazarević and Rilak, 2017)." (PMID 35401182, 2022). "This response promotes tumor catabolism and increases ubiquitin proteasomal degradation by accelerating phosphorylated cell signaling with transcriptional activator 3 (p-STAT3) and indoleamine 2,3-dioxygenase-1 (IDO1)." (PMID 35719333, 2022). "Nearly all the current inhibitors of Stat3 are low in potency (micro-molar), except the recently reported PROTAC-Stat3 inhibitors, including SD-36, which degrades cellular Stat3, with nanomolar potency and inhibits tumor growth." (PMID 35276290, 2022). "IL-6-mediated activation of the JAK/STAT3 signaling pathway by autocrine or paracrine means is required for malignant tumor proliferation." (PMID 36313280, 2022). "In line with the suppressive effect of STAT3 on NK-cell functionality reported in the murine system, tumor-derived cytokines, such as IL-6 and IL-8, impair human NK-cell function in a STAT3-dependent manner." (PMID 35865518, 2022). "Another research revealed that M2-polarized macrophages promote EMT of HCC cells and accelerate tumor progression through the TLR4/STAT3 signaling pathway." (PMID 36451087, 2022). "Napabucasin, a small molecule inhibitor of STAT3, impairs the stemness of GSLCs by inactivating p65/RelA involved in nuclear factor-κB heterodimer formation and suppress the tumor growth in an orthotopic xenograft model." (PMID 35740330, 2022). "Compared to the vehicle group, a TTF1-NP-treated mice group showed a smaller tumor size and reduced STAT3 and p-STAT3 protein expression." (PMID 36296934, 2022). "Data in the mouse MC38 tumor model suggest that TAM-derived milk-fat globule-epidermal growth factor-VIII (MFG-E8) mediates tumor chemotherapy resistance by activating STAT3 and Hedgehog signals in tumor stem cells." (PMID 35740594, 2022). "TAMs also protect ovarian cancer cells from anoikis by inducing the secretion of several soluble factors which promote the peritoneal dissemination of tumor cells and support their proliferation via STAT3 signaling." (PMID 35682890, 2022). "During the differential gene expression analysis of diosgenin-regulated genes, we observed that PDGFRB, FBFR2, and STAT3 possess maximum gene expression in tumor and metastatic vs." (PMID 36686654, 2022). "STAT3, which is continuously activated, promotes tumor cell proliferation and survival, stimulates angiogenesis, and inhibits the immune response to malignancy." (PMID 36324691, 2022). "GSEA demonstrated that the significantly positively enriched pathways in the low E6 ratio were cytosolic DNA sensing pathway, interferon-induced antiviral module, STAT3 targets, tumor differentiated, tumor evasion, and tolerogenicity." (PMID 36591476, 2022). "ITGA2 overexpression is essential for tumor development, metastasis, and motility, and this molecule triggers the overexpression of the STAT3 signaling pathway, thus promoting tumor progression." (PMID 36245988, 2022). "Similar results have been reported from studies on glioma and BC whereby TA-MSCs-secreted IL-6 increased the number of CSCs in tumor tissue and promoted proliferation and self-renewal of tumor cells through activating the STAT3 signal pathway." (PMID 35842634, 2022). "Conversely, blocking STAT3 significantly inhibits tumor growth by directly killing tumor cells and boosting antitumor immune responses." (PMID 36324587, 2022).